FGFR2 (fibroblast growth factor receptor 2)
Diseases named in the same sentence as FGFR2 in open-access papers (continued):
Sharing a sentence is not in itself a finding about the gene and the disease.
hemangioblastoma (1 paper, 2025). "Together with these previous reports, our results suggest a potential role of FGFR2 in the development and progression of VHL-mutated hemangioblastomas." (PMID 40393028, 2025). "In conclusion, our study highlighted the frequent expression of FGFR2 and FGFR4 in hemangioblastoma and revealed a correlation between larger tumor size and increased FGFR4 expression, suggesting their roles in tumor development and growth." (PMID 40393028, 2025). "One study examined a cohort of 20 VHL patients using laser-scanning cytometry and revealed elevated FGFR2 and FGFR3 expression in hemangioblastomas compared with clear-cell renal-cell carcinomas." (PMID 40393028, 2025). "Our analysis revealed FGFR2 expression in most of the hemangioblastoma samples, while FGFR3 were mostly negative." (PMID 40393028, 2025). "Our study revealed the expression of FGFR2 and FGFR4 in a significant number of hemangioblastomas." (PMID 40393028, 2025).
hepatoblastoma (1 paper, 2025). Hepatoblastoma (HB) is a malignant hepatic tumor and is the most common pediatric liver cancer. "The sialoblastoma from Patient 5 did not have an FGFR2 variant and instead showed a CTNNB1 missense hotspot variant (CTNNB1 p.I35T); the concurrent hepatoblastoma in this patient had a distinct CTNNB1 hotspot variant (CTNNB1 p.S45P)." (PMID 40906279, 2025).
hereditary cancer syndromes (1 paper, 2017).
Hypertelorism (1 paper, 2025). Interpupillary distance more than 2 SD above the mean (alternatively, the appearance of an increased interpupillary distance or widely spaced eyes). "Among them, mice with a deficiency for Fgfr1, Fgfr2, Kif3a, Kras, Ptch1, Rreb1, Sos1, and Tfap2a show excessive proliferation during midfacial development, resulting in hypertelorism, suggesting that mimics of miR-383-3p and miR-6951-3p activate cell proliferation through suppression of these genes." (PMID 40787625, 2025).
hypoparathyroidism (1 paper, 2019). Hypoparathyroidism is an endocrine disorder in which the parathyroid glands in the neck do not produce enough parathyroid hormone (PTH). "Similarly, both Gata3 which causes hypoparathyroidism, sensorineural deafness, renal anomaly (HDR) syndrome with uterine hypoplasia and Fgfr2, which causes disorders of sexual dimorphism in males, and decidualization defects in females, are highly expressed in the inhibited MISR2+ progenitors." (PMID 31232694, 2019).
infarction (1 paper, 2022). A localised pathological necrosis of tissue resulting from obstruction of the blood supply usually by a thrombus, an embolus, or vascular torsion. "One day after I/R injury, cardiac function, hypokinesis, and echocardiographic criteria of infarction were similarly affected in all three genotypes/conditions, suggesting that loss of cardiomyocyte FGFR1 and FGFR2 does not adversely affect cardiac function after I/R injury." (PMID 36211556, 2022).
invasive carcinoma (1 paper, 2023). A carcinoma that is not confined to the epithelium, and has spread to the surrounding stroma. "The early invasive carcinoma and two of four samples with intratumoral heterogeneity on TMA showed FGFR2 amplification." (PMID 36416959, 2023).
ischemia (1 paper, 2025). A hypoperfusion of the BLOOD through an organ or tissue caused by a PATHOLOGIC CONSTRICTION or obstruction of its BLOOD VESSELS, or an absence of BLOOD CIRCULATION. "We observed for the first time that the expression of FGFR2 gene was higher in ischemia-induced cortical penumbra compared to the sham group, while its expression was reduced in the calcitriol-treated group." (PMID 40791737, 2025).
ischemia reperfusion injury (1 paper, 2021). Adverse functional, metabolic, or structural changes in ischemic tissues resulting from the restoration of blood flow to the tissue (reperfusion), including swelling; hemorrhage; necrosis; and damage from free radicals. "FGFR1 and FGFR2 DKO mice, which exhibit endothelial cell-specific disruption of FGF2 function, have been shown to have significantly worsened cardiac function than controls after ischemia-reperfusion injury as well as significantly decreased vessel density." (PMID 34262947, 2021).
ischemic stroke (1 paper, 2025). A stroke disorder caused by obstruction of blood flow to the brain, due to thrombotic (local blood clot formation) or embolic (due to a blood clot or other material traveling from another site) event. "Despite the abundance of research on the effects of FGFRs in various diseases, there is no report of FGFR2 role in ischemic stroke." (PMID 40791737, 2025).
lymphoid leukaemia (1 paper, 2025). "Commonly, type II involves FGFR2-AFF3 and FGFR2-CASP7 gene fusions abnormally activating FGFR2 in breast cancer while type I concerns CNTRL–FGFR1 and ETV6–FGFR3 gene fusions leading to acute myeloid and lymphoid leukaemia patients." (PMID 40205008, 2025).
malignant mesothelioma (1 paper, 2021). A malignant neoplasm of the pleura or peritoneum, arising from mesothelial cells. "CD26, a cancer stem cell marker of malignant mesothelioma, has been shown to associate with the integrin α5β1 (or ITGA5, a novel interactor of the MPM gene, FGFR2) and promote cell migration and invasion in mesothelioma cells." (PMID 33916178, 2021).
memory impairment (1 paper, 2021). "Finally, three HGS genes, VLDR, FGFR2, and HBEGF, that are involved in synaptic plasticity and memory formation and belong to the red module—which is correlated with E-onset and memory impairment-showed significantly decreased expression in early disease onset patients." (PMID 33986407, 2021).
mesenchymal neoplasm (1 paper, 2025). "Here we describe the extremely rare entity of a “calcified chondroid mesenchymal neoplasm” (CCMN) with an FN1::FGFR2 fusion." (PMID 39404883, 2025).
metastatic colorectal cancer (1 paper, 2017). "At the pathway level, we detected that the alteration rate (mutation and copy number variation) of the genes involved in MAPK signaling pathways, including FGFR1, FGFR2, FGFR3, FGFR4, BRAF, and MEK, was significantly lower in metastatic colorectal cancer tissue compared to the primary site." (PMID 29038591, 2017).
microtia (1 paper, 2018). "Expression of FGFR2 in the ectoderm is the likely explanation for the microtia phenotype." (PMID 30266836, 2018).
mood disorder (1 paper, 2022). A cognitive disorder a disturbance in which the person's mood is hypothesized to be the main underlying feature. "Four of our 16 candidate proteins have previously been investigated in relation to mood disorders or suicide (FKBP5, FGFR2, SCGB1A1, and CD63), but most candidate proteins are novel to mood disorders and suicide research." (PMID 35697758, 2022).
multiple sclerosis (1 paper, 2024). A progressive autoimmune disorder affecting the central nervous system resulting in demyelination. "Deletion of Fgfr1 or Fgfr2 in oligodendrocytes was shown to inhibit myelin and axon degeneration in mouse models of experimental autoimmune encephalitis (a multiple sclerosis model)." (PMID 38638441, 2024).
myocardial infarction (1 paper, 2022). Gross necrosis of the myocardium, as a result of interruption of the blood supply to the area, as in coronary thrombosis. "Our studies elucidate that CD44 plays a key role in plasma exosomal miRNA-enhanced angiogenic FGFR2 singling transduction and ischemic angiogenesis in the early stage of myocardial infarction." (PMID 36463112, 2022).
myocardial ischemia (1 paper, 2013). A disorder of cardiac function caused by insufficient blood flow to the muscle tissue of the heart. "As FGF21 interacts with all known protein tyrosine kinase-coupled FGFRs, including FGFR1, FGFR2, FGFR3, and FGFR432, 36, 37, we tested the expression of these FGFRs in cardiomyocytes from wild-type mice with and without myocardial ischemia/reperfusion injury." (PMID 24067542, 2013).
nasal polyp (1 paper, 2024). "Tissue microarray (TMA) analysis further confirmed the elevation of FGFR2 in NPC tissues compared with in nasal polyp tissues (the first column)." (PMID 38637504, 2024).
neurocutaneous disorder (1 paper, 2024). "Taken together, considering the genotypic and phenotypic spectrum of the discussed disorders, FGFR2-associated neurocutaneous syndrome seems to be the most accurate clinical-molecular diagnosis for the individual reported here." (PMID 38265560, 2024). "Overall, our findings indicate FGFR2-associated neurocutaneous syndrome as the accurate clinical-molecular diagnosis for the reported individual, and thereby expand the complex genotypic and phenotypic spectrum of FGFR-associated disorders." (PMID 38265560, 2024).
nevus (1 paper, 2024). Nevus (or naevus, plural nevi or naevi, from nævus, Latin for "birthmark") is the medical term for sharply circumscribed[1] and chronic lesions of the skin or mucosa. "After in-depth filtering and variant interpretation, we identified a mosaic FGFR2 variant NM_000141.5:c.1647=/T > G p.(Asn549=/Lys) in the nevus sample." (PMID 38265560, 2024).
omphalocele (1 paper, 2020). Omphalocele is an embryopathy classified in the group of abdominal celosomias and is characterized by a large hernia of the abdominal wall, centered on the umbilical cord, in which the protruding viscera are protected by a sac. "Inactivating of one copy of Fgfr1 and both copies of Fgfr2 using a global inducible Cre causes omphalocele." (PMID 32907848, 2020). "Omphalocele is also observed in Fgfr1 heterozygotes, when Fgfr2 is also conditionally inactivated at E8.5 throughout the embryo." (PMID 32907848, 2020).
Osteochondroma (1 paper, 2023). A common, benign cartiliginous neoplasm arising from the metaphysis of bone. "Moreover, Judith et.al32 reported variation in expression of FGF2, FGFR2, FGFR3, PTHrP, and PTHrP‐R in osteochondroma samples from HME and non‐HME patient." (PMID 36162830, 2023).
ovarian endometriosis (1 paper, 2024). A non-neoplastic disorder characterized by the growth of endometrial tissue in the ovaries. "The upregulation of Fibroblast growth factor receptor 2 (FGFR2) expression in ovarian endometriosis demonstrates aberrant elevation during the progression towards malignancy." (PMID 38384812, 2024).
pancreatic acinar cell carcinoma (1 paper, 2022). An adenocarcinoma arising from the pancreas. "Fibroblast growth factor receptor-2 (FGFR2) fusions account for 3.5% of the genomic alterations KRAS WT PDAC and pancreatic acinar cell carcinoma." (PMID 36551707, 2022).
pancreatic NEN (1 paper, 2021). "Nintedanib is a dual inhibitor of VEGFR1, -2, and -3 as well as FGFR2 and showed both antiangiogenic and antitumor activity in the RIP1-Tag2 transgenic mouse model of tumorigenesis for pancreatic NEN." (PMID 33935975, 2021).
Pancreatoblastoma (1 paper, 2019). A rare malignant epithelial neoplasm arising from the pancreas. "Another case showed a pancreatoblastoma with an FGFR2::INA [fusion (case: #AMP-4)." (PMID 31491926, 2019).
pediatric cancers (1 paper, 2025). "Using a broad search of all pediatric cancers, we observed the rates of alterations of the FGFR1, FGFR2, FGFR3, and FGFR4 genes in pediatric cancers to be 0.5%, 0.1%, 1.1%, and 0.8%, respectively." (PMID 40510032, 2025).
periodontitis (1 paper, 2022). An acute or chronic inflammatory process that affects the tissues that surround and support the teeth. "Our study provides novel evidence that miR-223 can be induced by periodontitis and acts as a negative regulator of PDL-derived cells osteogenesis by targeting two growth factor receptors (TGFβR2 and FGFR2)." (PMID 36221121, 2022). "In summary, we have demonstrated that miR-223 can be induced by periodontitis and acts as a negative regulator of PDL-derived cells osteogenesis by targeting two growth factor receptors (TGFβR2 and FGFR2)." (PMID 36221121, 2022).
Pfeiffer syndrome type 3 (1 paper, 2021). Pfeiffer syndrome type 3 (PS3) is a severe type of Pfeiffer syndrome (PS), characterized by bicoronal craniosynostosis, severe associated functional disorders, and hand, foot and elbow abnormalities. "A diagnosis of Pfeiffer syndrome type 3 with FGFR2 c.1052C>G (p.Ser351Cys) variant was made." (PMID 34909104, 2021).
portal hypertension (1 paper, 2013). Increased blood pressure in the portal venous system. "It is likely that patients with a lower platelet count had more severe portal hypertension and that the vascular derangements secondary to portal hypertension lead to the decreased expression of the receptors for proangiogenic factors like FGFR1, FGFR2, and VEGFR2." (PMID 23620752, 2013).
prostate tumors (1 paper, 2022). "Taken together with evidence that FGF7 activates FGFR2 in FP‐RMS cells, our data strongly support this ligand‐receptor pairing forming an autocrine loop promoting FP‐RMS cell viability and survival in a similar fashion to that observed in prostate tumors and pre‐adipocytes." (PMID 34850536, 2022).
renal dysplasia (1 paper, 2012). Renal dysplasia is a form of renal malformation in which the kidney(s) are present but their development is abnormal and incomplete. "In sharp contrast, Fgfrl1 null mice have a phenotype with renal dysplasia very similar to mice with a conditional disruption of Fgf8 or a compound disruption of the two receptors Fgfr1 and Fgfr2." (PMID 22432025, 2012).
silicosis (1 paper, 2021). Silicosis is a respiratory disease caused by breathing in (inhaling) silica dust. "Except one gene (FGFR2), all other genes we tested had significantly altered mRNA levels in the lungs of patients with silicosis, the same trends as revealed by RNA-seq." (PMID 34149803, 2021). "In our results, the pathway of lung epithelial progenitor cell differentiation, including several essential genes (e.g., FGF10, FGFR2), was remarkably down-regulated in silicosis, indicating disordered respiratory epithelium regeneration in the disease progression." (PMID 34149803, 2021).
steatosis (1 paper, 2012). Increased lipid within the cytoplasm of cells. "Adipocyte-specific deletion of FGFR isotypes, FGFR1 and FGFR2 show that specifically adipose FGFR1 mediates indirect effects in liver that are most significant under starvation conditions which causes hepatic stress and steatosis." (PMID 23106963, 2012).
Strabismus (1 paper, 2025). A misalignment of the eyes so that the visual axes deviate from bifoveal fixation. "The effect on extraocular muscles and the resultant strabismus is not surprising, as human fetal extraocular muscles express FGFR2." (PMID 40894678, 2025).
synovial sarcoma (1 paper, 2013). "Upregulation of FGFR2 in synovial sarcoma has been linked to the synovial sarcoma-associated oncogene SYT–SSX2." (PMID 24204904, 2013).
Thrombocytopenia (1 paper, 2013). A reduction in the number of circulating thrombocytes. "Diminished expressions of PDGFB and VEGFR2, FGFR1, and FGFR2 were well correlated with the degree of thrombocytopenia in these cirrhotic patients (ρ>0.5, p<0.001)." (PMID 23620752, 2013). "These diminished expressions of PDGFB, VEGFR2, FGFR1, and FGFR2 were well correlated with the degree of thrombocytopenia in the cirrhotic patients." (PMID 23620752, 2013).
thyroid tumor (1 paper, 2013). A benign or malignant neoplasm affecting the thyroid gland. "In light of these considerations, we decided to assess FGFR-2 expression evaluating their relevance in thyroid tumors progression and diagnosis." (PMID 23977259, 2013). "The present study is aimed to update information about FGFR-2 expression in different histological thyroid types and its potential correlation with thyroid tumor progression." (PMID 23977259, 2013). "The choice of FGFR-2 is justified by its role in the formation of thyroid follicular gland and its suggested involvement in thyroid tumor progression." (PMID 23977259, 2013). "In particular, it is known that normal human thyroid tissue expresses FGFR-2, while it is not detectable in thyroid tumor cell lines." (PMID 23977259, 2013).
ulcerative colitis (1 paper, 2021). An inflammatory bowel disease involving the mucosal surface of the large intestine and rectum. "Furthermore, activating FGFR2 mutations occur in nondysplastic colorectal mucosa from ulcerative colitis patients, together with defects of the E-cadherin-encoding suppressor gene CDH1." (PMID 34007277, 2021).
Urethral stricture (1 paper, 2022). Narrowing of the urethra associated with inflammation or scar tissue. "Double-modified sulfonated bacterial cellulose scaffolds combined with FGFR2-modified ADSCs provide new sight and treatments for patients with urethral strictures." (PMID 36068613, 2022). "Urethral leakage or severe urethral stricture resulted in the death of one New Zealand rabbit in each of the negative control and FGFR2 ctrl groups at 3 months." (PMID 36068613, 2022).
urinary system cancer (1 paper, 2014). "Indeed, EGF/EGFR, FGFR2, KLK3, and PDGFRB were reported to play important roles in urinary system cancer development and progression." (PMID 24801713, 2014).
uterine serous carcinoma (1 paper, 2022).
vesicoureteral reflux (1 paper, 2013). Abnormal flow of urine from the urinary bladder back into the ureters. "Pax3cre-mediated deletion of fibroblast growth factor receptor 2 (Fgfr2) broadly in renal and urinary tract mesenchyme led to ureteric bud (UB) induction defects and vesicoureteral reflux (VUR), although the mechanisms were unclear." (PMID 23409123, 2013).